SNORA7A (small nucleolar RNA, H/ACA box 7A)
Synonyms: ACA7
Gene: Small nucleolar RNA gene on chromosome 3 (12,840,312 to 12,840,450, reverse strand). Ensembl gene ENSG00000207496.
Gene Ontology:
Biological process: RNA processing
Cellular component: nucleolus
Homologues: Orthologues: chimpanzee SNORA7A (100% identical), mouse Snora7a (88% identical), rat LOC120102637 (88% identical). Paralogues in human: SNORA7B (99% identical).
Diseases named in the same sentence as SNORA7A in open-access papers:
SNORA7A is named in the same sentence as 1 disease in open-access papers, as found by Europe PMC text mining. Sharing a sentence is not in itself a finding about the gene and the disease.
SNORA7A shares sentences with these, for which no sentence is quoted: Tumor (1 paper).